CRP (C-reactive protein)
Diseases named in the same sentence as CRP in open-access papers (continued):
Sharing a sentence is not in itself a finding about the gene and the disease.
Autoimmunity (continued). "Thus, it may play a crucial role in activating the immune response prior to the development of an adaptive immune response, and also, CRP as a pentraxin generally controls inflammation and autoimmunity in many ways." (PMID 37873776, 2023). "Also, it is yet unknown if the infant could recognize this CRP as an antigen and therefore have a possibility for autoimmunity." (PMID 37873776, 2023). "In this sense, the objective of the present study was to identify polymorphisms in important mediators of the immune response (FOXP3, IFNG, IL6, IL8, IL10, MBL2, CRP, TGFΒ1 and TNFA) in association with ANAs, which could contribute to the development of autoimmunity in hepatitis C." (PMID 32743104, 2020). "CRP increases clearance of apoptotic cells, binds to nuclear antigens and by masking autoantigens from the immune system or enhancing their clearance, CRP has been hypothesized to prevent autoimmunity." (PMID 24457057, 2014). "Acute phase proteins such as C-reactive protein (CRP) have been well recognized for their application in human diagnostic medicine and have been described to have value in the diagnosis and prognosis of cardiovascular disease, autoimmunity, organ transplant, and cancer treatment." (PMID 24223742, 2013). "Since store-operated calcium entry is important in T cell-mediated autoimmunity, our results implied that polymorphisms of STIM1 may influence store-operated calcium signals which in turn involve the regulation of cytokine release and ESR/CRP expression." (PMID 23272049, 2012). "This is reasonable, as a positive correlation between CRP levels and HMGB1 was described before (in the setting of autoimmunity and inflammation;)." (PMID 34671818, 2022). "C-reactive protein (CRP) is a widely used marker of inflammation of clinical importance especially in infection, but also in autoimmunity." (PMID 35243104, 2022). "The association between the maturation of PR3+ B cells, as reflected by the IgD– memory/naive ratio, with CRP, ESR, and complete remission suggests a link between autoimmunity and systemic inflammation in AAV." (PMID 34618687, 2021). "This review summarizes recent discoveries related to CRP-mediated biological effects, as well as to the regulation of CRP release with respect to aspects of CVD and mechanisms of autoimmunity." (PMID 34945133, 2021). "In line with a potential role in autoimmunity, the elevated Gal-9 serum levels in RA patients correlated with disease activity scores (DAS-28) and CRP, particularly in current and ex-smokers." (PMID 31430907, 2019). "Univariate analyses showed that patients with autoimmune conditions had higher IgG levels but also lower white blood cell counts (WBC) and hemoglobin (Hgb), hematocrit, complement and CRP levels." (PMID 24180594, 2013). "These include serum inflammatory markers such as C-reactive protein (CRP) and erythrocyte sedimentation rate (ESR), as well as markers of autoimmunity, including antinuclear antibodies (ANA), rheumatoid factor (RF), and anti-citrullinated protein antibodies (ACPA)." (PMID 40572738, 2025). "Demographic data, serum inflammatory markers such as C-reactive protein (CRP) and erythrocyte sedimentation rate (ESR), and autoimmunity markers including antinuclear antibodies (ANA), rheumatoid factor (RF), and anti-citrullinated protein antibodies (ACPA) were evaluated." (PMID 40572738, 2025). "Among all the antibodies with differences, 12 IgG antibodies against Jo-1, SSB, PL-12, PM/scl100, Scl-70, TIF1γ, β-actin, MPO, TTG, AQP4, calprotectin, and CRP were more abundant in patients with autoimmunity than in those without (p < 0.05)." (PMID 38634985, 2024). "Following the APPs, the C-reactive protein (CRP) is a positive APP that increases its levels under a stimulus that according to its function protects against infection and regulates the inflammation response and autoimmunity." (PMID 38250291, 2024).
Autoimmunity (continued). "However, debate continues over whether CRP is primarily a passive indicator of inflammatory events, a “culprit” mediating disease, or nature’s own immunosuppressant, functioning to limit tissue damage, modulating acute inflammation, and preventing autoimmunity." (PMID 19690638, 2007). "Further studies should also investigate the association between baseline inflammatory burden and blood pressure responses to methotrexate in patients with RA, other autoimmune disorders, and patients without autoimmune disorders and a wide range of CRP concentrations." (PMID 40742006, 2025). "Furthermore, the AUC value for autoimmune conditions was 0.71 (95% CI 0.70–0.72) for CRP and 0.71 (95% CI 0.69–0.72) for ESR whereas the AUC for combined CRP and ESR was marginally higher, 0.72 (95% CI 0.71–0.74), but still considerably below that observed for SAA in our study." (PMID 38951267, 2024). "Patients who suffered from autoimmune conditions and other diseases that could affect baseline CRP values were also not excluded from the analysis to maintain sufficient statistical power." (PMID 38003780, 2023). "Concerning the immune-biological monitoring, the best outcome in patients with lower systemic inflammatory baseline profile (neutrophil counts, NLR, CRP,ESR, LDH/LDHNV, and ENA) and higher baseline levels of IL-4, which may promote occurrence of auto-antibody-driven autoimmunity, was found." (PMID 29755670, 2018). "Additional EAE studies showed that human CRP's ability to ameliorate disease in CRPtg depends on its ability to engage the inhibitory type IIB Fc gamma receptor (FcγRIIB), a finding which may partially explain the tonic suppressive effect of CRP on T cell-driven autoimmunity." (PMID 26421184, 2015). "Highlights included increased sedimentation rate (36 mm/h) and C-reactive protein (CRP) level, in addition to a negative autoimmunity panel and blood cultures." (PMID 39735473, 2024).
liver cirrhosis (74 papers, 2012 to 2026). "None of the SM species were associated with ALT, AST, albumin, CRP, leukocytes, platelet count, or creatinine in male patients with liver cirrhosis." (PMID 37176109, 2023). "Impaired hepatocyte function and accordingly CRP synthesis limit the diagnostic value of CRP in patients with decompensated liver cirrhosis." (PMID 32078718, 2020). "The increased serum levels of inflammatory markers (such as C-reactive protein, white blood cell count and IL-6) found in patients with liver cirrhosis have been implicated in the breakdown of the blood–brain barrier." (PMID 23406548, 2013). "Whether plasma LBP levels in critically ill patients with liver cirrhosis are similarly reduced as CRP or change in patients with underlying pancreatitis needs to be evaluated." (PMID 39997462, 2025). "Serum CRP, which is known as an inflammation marker, is associated with the development of HE and can serve as a predictor of adverse outcomes and increased risk of HE in patients hospitalized with liver cirrhosis." (PMID 40768760, 2025). "It is worth noting that the increase in C-reactive protein, the most commonly used clinical marker of inflammation, is reduced in patients with liver cirrhosis in response to infection." (PMID 39948564, 2025). "Elevated CRP levels can diagnose SI and are significantly correlated with poor prognosis in liver cirrhosis." (PMID 40747208, 2025). "The inflammatory markers procalcitonin and CRP are reduced in patients with liver cirrhosis, a group excluded from our study." (PMID 41007672, 2025). "In line with this assumption, positive correlations between plasma PCSK9 and the markers of inflammation, namely CRP, leukocyte count, and procalcitonin were only detected in patients with liver cirrhosis." (PMID 37515197, 2023). "Comparison of the entire study cohort with the subgroup of patients with liver cirrhosis showed that the subgroup of patients with liver cirrhosis had low levels of the C-reactive protein (CRP) in comparison with the whole cohort." (PMID 37515197, 2023). "The correlation of chemerin with CRP remained significant after the exclusion of patients with liver cirrhosis (r = 0.384, p < 0.001)." (PMID 37509420, 2023). "Many studies have shown that increased C-reactive protein (CRP) can lead to complications such as liver cirrhosis and fibrosis in the chronic phase of hepatitis B." (PMID 36411916, 2022). "Significant differences between the healthy volunteer group with the liver cirrhosis group were found upon comparison, whereby the liver cirrhosis group had lower albumin values (p < 0.0001) and higher CRP values (0.0007)." (PMID 36553020, 2022). "Studies have found that liver cirrhosis patients with infection have significantly higher serum endocan, CRP, TNF-α and procalcitonin levels." (PMID 35071362, 2021). "At 12 weeks posttreatment, the associations of serum PCSK9 with the MELD score, bilirubin, INR, leukocytes and CRP in the patients with liver cirrhosis persisted." (PMID 33920491, 2021). "Remarkably, the S100A8/CRP ratio was found at similar rates in patients with miliay tumor spread when compared to patients with liver cirrhosis." (PMID 32098278, 2020). "As expected patients with liver cirrhosis had higher serum bilirubin (3.07 vs. 0.96 mg/dL; p < 0.001), C-reactive protein (36.9 vs. < 5 mg/L), and INR (1.53 vs. 0.95; p < 0.001; respectively) than controls." (PMID 32808849, 2020). "CRP and GSH had exerted synergistic effects in the association with the severity of liver cirrhosis." (PMID 29861471, 2018). "CRP and GSH levels, which had showed interactions, were associated with the severity of liver cirrhosis." (PMID 29861471, 2018). "In patients with decompensated liver cirrhosis, PCT showed the best diagnostic value relative to C-reactive protein (CRP), interleukin-6, and tumor necrosis factor-α." (PMID 29849829, 2018).
liver cirrhosis (continued). "The sensitivity and specificity of CRP for liver cirrhosis patients with SBP were 75% and 61.2%, respectively (AUC: 0.613, CI 95%: 0.532-0.724, p<0.01)." (PMID 28083050, 2016). "Oral administration of BCAA granules decreased highly sensitive CRP in HCV-positive patients with liver cirrhosis." (PMID 26593945, 2015). "In patients with liver cirrhosis, elevated systemic IL-22 levels are predictive for reduced survival independently from age, liver-related complications, CRP, creatinine and the MELD score." (PMID 22967278, 2012). "IL-22 also correlated with CRP, a well-established surrogate marker of hepatic inflammation and prognosis of liver cirrhosis." (PMID 22967278, 2012). "On the other hand, patients with liver cirrhosis have higher CRP in comparison to healthy controls because liver cirrhosis may lead to a systemic state of inflammation." (PMID 39997462, 2025). "BMI, CRP, age, sex, and liver cirrhosis predicted plasma adiponectin with a p < 0.001 (F(6/146)." (PMID 38137508, 2023). "The initial platelet count and the necessity of platelet transfusion was not correlated with any associated diagnoses (liver cirrhosis and urosepsis), CRP, ALT, BUN, or creatinine levels." (PMID 37958881, 2023). "Notably, patients with liver cirrhosis exhibit reduced CRP levels due to impaired hepatic synthesis, while procalcitonin levels in individuals with severe liver diseases tend to be elevated." (PMID 38137508, 2023). "Patients with liver cirrhosis had low CRP levels in comparison with the other subgroups." (PMID 37515197, 2023). "Thus, serum CRP has been demonstrated to be a predictor due to an increase of its serum level in acute urinary retention, acute prostatitis, and liver cirrhosis." (PMID 36110189, 2022). "Furthermore, reduced production of acute- phase proteins, such as C-reactive protein (CRP), in patients with decompensated liver cirrhosis, made them had a weaker severity prediction and stratification ability in response to infection." (PMID 32376846, 2020). "It is also recognized that CRP is increased in people with liver cirrhosis and MHE." (PMID 25658922, 2015). "Moreover, C-reactive protein (CRP), the most widely used marker for screening inflammation, is produced by the liver; thus, the CRP response to inflammation could be slow and inadequate as the liver cirrhosis worsens due to the deterioration of liver function." (PMID 37761321, 2023). "In more detail, levels of the pro-inflammatory mediators CRP, tPA, IL-6, IL-8, HGF, M-CSF, IL-2Ra, IP-10, and MIP-1a were significantly increased in patients with decompensated liver cirrhosis compared with healthy controls." (PMID 41028194, 2025). "Of note, negative associations of serum PCSK9 with the MELD score, ALT, bilirubin, INR and CRP and positive correlations with albumin and leukocyte count existed in the HCV patients with liver cirrhosis." (PMID 33920491, 2021). "According to a meta-analysis, both CRP and PCT showed acceptable accuracy for diagnosing bacterial infections in patients with liver cirrhosis." (PMID 32899730, 2020). "Other biomarkers, such as CRP or PCT, are commonly known and have been thoroughly studied in patients with decompensated liver cirrhosis, ascites, and SBP." (PMID 30363905, 2018). "In agreement, several studies have shown that CRP levels are downregulated in HCV patients and plasma fibrinogen concentration progressively decreases as liver cirrhosis worsened in patients with hepatic-nephrotic disease." (PMID 30540839, 2018). "Since inflammatory responses and antioxidant capacities have not been examined in the previous studies regarding their possible interactions, the synergistic effects of CRP and GSH on the severity of liver cirrhosis cannot be ignored." (PMID 29861471, 2018). "Several markers (HBP, CRP, PCT, WBC, and D-dimers) were analysed in blood serum in regard to their potential use in the diagnosis of SBP in patients with decompensated liver cirrhosis and ascites." (PMID 30363905, 2018).
liver cirrhosis (continued). "In a recent meta-analysis including 1144 patients with liver cirrhosis, AUC for PCT and CRP was, respectively, 0.92 (95% CI: 0.89-0.94) and 0.87 (95% Cl: 0.84-0.90)." (PMID 31582968, 2018). "Although patients with liver cirrhosis typically exhibit low CRP levels, excluding these patients did not alter this finding (r = -0.072, p = 0.374)." (PMID 39948564, 2025). "At the end of treatment, LPC species did not correlate with CRP and leukocyte count in patients with and without ultrasound-diagnosed liver cirrhosis (p > 0.05 for all)." (PMID 38256273, 2024). "In liver cirrhosis, PC species were not related with CRP, the leukocyte count or platelets (p > 0.05 for all)." (PMID 39125730, 2024). "A comparison of the whole study cohort and the subgroup of patients without liver cirrhosis showed that this latter group had higher levels of C-reactive protein (CRP)." (PMID 38137508, 2023). "The correlations with CRP (r = −0.160, p = 0.079) and procalcitonin (r = 0.153, p = 0.099) were not significant when patients with liver cirrhosis were excluded, whereas IL-6 still positively correlated with sCD137 (r = 0.202, p = 0.029)." (PMID 38139346, 2023). "Serum SM species levels did not correlate with the MELD score, ALT, AST, bilirubin, albumin, INR, CRP, leukocytes, platelet count, or creatinine in female patients without liver cirrhosis (p > 0.05)." (PMID 37176109, 2023). "The levels of serum SM species did not correlate with alanine aminotransferase (ALT), aspartate aminotransferase (AST), bilirubin, C-reactive protein (CRP), leukocytes, platelets, or creatinine in female patients with or without liver cirrhosis." (PMID 37176109, 2023). "Serum SM species levels did not correlate with the MELD score, ALT, AST, bilirubin, albumin, INR, CRP, leukocytes, platelets, or creatinine in male patients without liver cirrhosis (p > 0.05)." (PMID 37176109, 2023). "We investigated the ability of white blood cell (WBC), ∆WBC, neutrophil and ∆neutrophil counts, neutrophil-to-lymphocyte (NLR) and ∆NLR ratios and C-reactive protein (CRP) and procalcitonin (PCT) levels to identify infection and predict short-term mortality in liver cirrhosis patients." (PMID 37761321, 2023). "In the uninfected group of liver cirrhosis, the endocan level is not correlated with other indicators, while in the infected group, the endocan level was correlated with the child-Pugh score, CRP, and TNF-α levels." (PMID 35071362, 2021). "For example, the acute-phase proteins C-reactive protein (CRP) and procalcitonin (PCT) are commonly evaluated “biomarkers” for identification of infectious diseases and prediction of prognosis in patients with liver cirrhosis." (PMID 32899730, 2020). "We demonstrate herein that elevated systemic IL-22 levels are predictive for reduced survival in patients with liver cirrhosis independent of age, presence of liver-related complications, CRP, creatinine and the MELD score." (PMID 22967278, 2012). "It is possible that the negative correlation of sCD137 with CRP is related to the slightly higher levels of sCD137 and the reduced levels of CRP in liver cirrhosis, and the correlation of CRP and sCD137 was not significant after the exclusion of patients with liver cirrhosis." (PMID 38139346, 2023). "In patients with liver cirrhosis, plasma LBP was also positively correlated with procalcitonin (r = 0.480, p = 0.004) and CRP (r = 0.703, p < 0.001) but not with IL-6 and immune cell numbers." (PMID 39997462, 2025). "In the subgroup of patients with liver cirrhosis, none of the LPC species were related with CRP, leukocyte count or platelets." (PMID 38256273, 2024). "In patients without liver cirrhosis, LPC species did not correlate with C-reactive protein (CRP) or leukocyte count." (PMID 38256273, 2024). "For predicting infection using the logistic regression analysis, old age, female gender, non-alcohol related liver cirrhosis, the presence of SIRS, high level of CRP and NLR were significant factors." (PMID 26498833, 2015).
liver cirrhosis (continued). "Thus, we considered the lower CRP and LRINEC score were related to rapidly progressive and fulminant course of V. vulnificus NF, not related to liver cirrhosis." (PMID 34372768, 2021). "Patients with liver cirrhosis and IPA did not have significantly increased neutrophil numbers (p = 0.253) or proportions (p = 0.137); however, they had higher than normal CRP levels, which may be a clue for the diagnosis of IPA and liver cirrhosis while combined with imaging findings." (PMID 24401649, 2014).